PBX3 (PBX homeobox 3)
Diseases named in the same sentence as PBX3 in open-access papers (continued):
Sharing a sentence is not in itself a finding about the gene and the disease.
cervical cancer (5 papers, 2020 to 2023). A primary or metastatic malignant neoplasm involving the cervix. "The knockdown of PBX3 in cervical cancer cells was found to inhibit cell proliferation in vitro and tumour size and weight in vivo via the inactivation of the PI3K/AKT signalling pathway via downregulating p‐AKT expression." (PMID 35068042, 2022). "The miR-526b miRNA was reduced in various cancers, including cervical cancer and miR-526b expression leads to a decrease in Pbx3 expression in cervical cancer cells when compared to healthy cells." (PMID 33402862, 2020). "PBX3 is overexpressed in the cytoplasm of cervical cancer cells and tissues and its expression is related to poor prognosis, tumor diameter, pathological grade, clinical stage lymph node metastasis, invasion depth, and vascular invasion." (PMID 33402862, 2020). "Moreover, the PBX3-mediated epithelial-to-mesenchymal transition (EMT) process is associated with invasion and metastasis that is inhibited by miR-526b in cervical cancer cells." (PMID 33402862, 2020). "PBX3 is highly expressed in a variety of cancer tissues, such as prostate and cervical cancer." (PMID 32487167, 2020). "The function of PBX3 is likely controlled by the AKT signaling pathway in cervical cancer." (PMID 33402862, 2020).
melanoma (5 papers, 2020 to 2022). A malignant, usually aggressive tumor composed of atypical, neoplastic melanocytes. "MiR‐4458 inhibited cell proliferation and migration, yet induced apoptosis in melanoma by directly targeting PBX3." (PMID 35068042, 2022). "Overexpression of miR‐320a inhibited cell migration and EMT of melanoma cells by directly targeting PBX3." (PMID 35068042, 2022). "In contrast, HuR, which is overexpressed in melanoma, stabilizes PBX3 mRNA by competing with miR-4458." (PMID 35884580, 2022). "Overexpression of miR‐495 repressed cell proliferation, migration and invasion in melanoma by directly targeting PBX3." (PMID 35068042, 2022). "For instance, serum miR-320a was proved to directly bind to PBX3 protein in melanoma and inhibit the malignant phenotype of cells and affects the occurrence and progression of melanoma." (PMID 35201481, 2021).
colon cancer (4 papers, 2019 to 2023). "Silencing PBX3 in colon cancer (CC) cells partially reversed the decreased expression of E‐cadherin induced by Snail, whereas PBX3 knockdown upregulated the expression of E‐cadherin." (PMID 35068042, 2022). "PBL PBX3 hypermethylation is positively associated with better prognosis of CRC, especially for the UICC stage III CRC patients and colon cancer patients." (PMID 31140752, 2019). "PBX3 can reverse the inhibitory effect of Let-7c on colon cancer growth." (PMID 35342419, 2022). "Our findings in PBL of CRC patients with 10‐year follow‐up data suggest that PBX3 hypermethylation is an independent predictor to better OS of CRC patients, especially in patients with stage III or colon cancer." (PMID 31140752, 2019). "Subgroup analyses showed that the beneficial effect of PBX3 hypermethylation status on CRC 10‐years OS remained significant among UICC stage III patients ([HRPS‐adjusted], 0.60 [95% CI, 0.38 to 0.95]; P = 0.029) and colon cancer patients ([HRPS‐adjusted], 0.49 [95% CI, 0.26 to 0.92]; P = 0.027)." (PMID 31140752, 2019). "First, PBL PBX3 hypermethylation was significantly associated with a better OS and obviously correlated with a longer OS time in a collection of 144 stage III CRC patients or in 129 patients with colon cancer, while this was independent of other core clinical variables." (PMID 31140752, 2019).
papillary thyroid carcinoma (4 papers, 2020 to 2022). "However, the contribution of PBX3 to papillary thyroid carcinoma (PTC) remains unclear." (PMID 32047817, 2020).
breast carcinoma (3 papers, 2022 to 2023). "Taken together, these results demonstrated that ATRAP regulates aggressiveness in breast cancer cells via PBX3." (PMID 35414770, 2022). "Our study demonstrates the broad contribution of the USF1/ATRAP/PBX3 axis to breast cancer progression and provides a strong potential therapeutic target." (PMID 35414770, 2022). "Specifically, leptin significantly increased PBX3 mRNA expression by enhancing the activity of the PBX3 promoter in a STAT3‐dependent manner in breast cancer (BC) cells." (PMID 35068042, 2022). "Our study identified PBX3 as a target of ATRAP in breast cancer cells, and there is ample evidence that ATRAP binds to PBX3, protecting it from proteasomal degradation." (PMID 35414770, 2022). "Furthermore, we found that in clinic, high levels of ATRAP combined with upregulation of USF1 and PBX3 can serve as a potentially reliable prognostic indicator for breast cancer patient outcomes." (PMID 35414770, 2022). "Rescue assay showed that ATRAP regulates breast cancer cell progression via PBX3." (PMID 35414770, 2022). "Similar effects to those with ATRAP knockdown were observed in PBX3 knockdown breast cancer cells." (PMID 35414770, 2022). "We also showed that PBX3 participates in ATRAP-mediated breast cancer progression." (PMID 35414770, 2022). "To determine whether PBX3 participates in ATRAP-mediated breast cancer progression, we generated a PBX3 siRNA knockdown line in UACC-812 cells." (PMID 35414770, 2022). "However, the precise molecular mechanisms by which USP14 interacts with PBX3 in breast cancer remain unclear." (PMID 35414770, 2022). "To further examine the relationship between ATRAP and human breast cancer, we performed IHC staining of ATRAP, PBX3, and USF1 in 49 breast cancer patient specimens." (PMID 35414770, 2022). "In contrast, MDA-MB-453 and MCF7 breast cancer cells exhibited relative low expression of USF1, ATRAP and PBX3." (PMID 35414770, 2022). "Consistent with our observations, the distribution and intensity of ATRAP were both positively correlated with PBX3 and USF1 in breast cancer tissue specimens." (PMID 35414770, 2022). "Subsequently, we examined the protein expression levels of USF1, ATRAP and PBX3 in breast epithelial cell (MCF10A) and 7 breast cancer cell lines." (PMID 35414770, 2022). "Therefore, the USF1/ATRAP/PBX3 axis activates AKT/mTOR signaling and promotes breast cancer aggressiveness." (PMID 35414770, 2022).
liver cancer (3 papers, 2019 to 2022). An epithelial or non-epithelial malignant neoplasm that arises from the liver. "miR-33a-3p can reduce the invasion and migration capability of liver cancer cells through the targeted inhibition of PBX3." (PMID 35342419, 2022). "In this study, the expression of miR-302a and MAP3K2/PBX3 were evaluated by qPCR in liver cancer cell lines." (PMID 30765768, 2019). "And miR-302a, MAP3K2 and PBX3 expression levels were detected in liver cancer cells and tissues." (PMID 30765768, 2019). "The results showed that liver cancer cell lines exhibited low miR-302a expression and MAP3K2 and PBX3 were confirmed to be the target genes of miR-302a." (PMID 30765768, 2019).
lung carcinoma (3 papers, 2017 to 2022). "In lung cancer cells, circNBPF10 negatively regulated the expression of miR-224, whereas miR-224 directly targeted the expression of PBX3." (PMID 35342419, 2022). "Overexpression of lncRNA UCA1 significantly promoted lung cancer cell viability, migration, invasion, and cell cycle progression, but promoted cell apoptosis by upregulating PBX3 via sponging miR‐144." (PMID 35068042, 2022). "The results of the rescue experiment confirmed that PBX3 was the key gene for the promoting effect of circNBPF10 on the malignant progression of lung cancer." (PMID 35342419, 2022). "This study aimed to describe the regulatory role of the circNBPF10/miR-224/PBX3 axis in lung cancer and to describe the cellular/molecular mechanisms of this role." (PMID 35342419, 2022). "circNBPF10 upregulated PBX3 by targeting miR-224 and promoted the malignant progression of lung cancer." (PMID 35342419, 2022). "circNBPF10 targeted miR-224 to upregulate the expression of PBX3 and thus aggravated the malignant progression of lung cancer." (PMID 35342419, 2022). "In addition, the role of pre-B-cell homeo box 3 (PBX3) in the progression of lung cancer affected by circNBPF10 was evaluated through a rescue experiment." (PMID 35342419, 2022).
myoepithelioma (3 papers, 2015 to 2021). "This was because PBX3 has extensive homology to PBX1 which has been found as a 3 ́-partner in an EWSR1-PBX1 fusion in myoepithelial tumors." (PMID 25875009, 2015).
pancreatic cancer (3 papers, 2020 to 2022). "Overexpression of miR‐129‐5p overexpression inhibited the proliferation, migration and invasion, and induced apoptosis of pancreatic cancer cells by directly targeting PBX‐3." (PMID 35068042, 2022). "MiR-129-5p is also a tumor suppressor in pancreatic cancer, and it is reported that miR-129-5p exerts a tumor-suppressive effect in pancreatic cancer progression via targeting PBX3." (PMID 34660566, 2021).
astrocytoma (2 papers, 2018 to 2024). "The top positive gene, PBX3, is a transcription factor previously implicated in certain astrocytomas." (PMID 29617658, 2018).
congenital heart defects (2 papers, 2018 to 2021). "The zebrafish study on pbx3 identified its potential new role as a modifier in congenital heart defects." (PMID 34698193, 2021).
embryonal carcinoma (2 papers, 2011 to 2022). A non-seminomatous malignant germ cell tumor characterized by the presence of large germ cells with abundant cytoplasm resembling epithelial cells, geographic necrosis, high mitotic activity, and pseudoglandular and pseudopapillary structures formation. "The expression of PBX1, PBX2, and PBX3 was upregulated during endodermal and neuronal differentiation of embryonal carcinoma P19 cells in a RAR‐dependent subtype‐unspecific manner following RA treatment." (PMID 35068042, 2022). "Previous studies have shown that all-trans retinoic acid induced the expression of PBX1 at mRNA level in P19 embryonic carcinoma cells, whereas the PBX3 mRNA level remained unchanged." (PMID 21548940, 2011).
co-infection (1 paper, 2021). "Notably, the protein levels of PBX3 were also assessed under co-infection of LV-CD27-AS1 and LV-miR-224-5p in HL-60 and KG-1 cells." (PMID 34006845, 2021).
diabetes (1 paper, 2020). "Specially, miR-150 targets gene pre-B-cell leukemia transcription factor 3 (pbx3), further regulating immune response, homeostasis and metabolism including incidence of diabetes and mortality from cancer." (PMID 32087063, 2020).
gastric tumors (1 paper, 2023). "For instance, SNHG10 promotes the growth and migration of gastric tumors by targeting the miR-495-3p/CTNNB1 axis, activating the WNT pathway and the DDX54-mediated PBX3 feedback pathway." (PMID 36871072, 2023).
laryngeal carcinoma (1 paper, 2024). Carcinoma that arises from the laryngeal epithelium. "In laryngeal cancer, let-7c-5p was downregulated in tumours and controlled the Pre-B-cell leukaemia homeobox transcription factor 3 (PBX3)." (PMID 38899393, 2024).
neuroblastoma (1 paper, 2021). Neuroblastoma (NB) is the most common solid, extracranial childhood tumor. "ARNT2 and PBX3 expressions were lower in ES cell line RD-ES than neuroblastoma cell line SH-5Y5Y (p < 0.001)." (PMID 33924679, 2021).
pneumonia (1 paper, 2021). An acute, acute and chronic, or chronic inflammation focally or diffusely affecting the lung parenchyma, caused by an infection in one or both of the lungs (by bacteria, viruses, fungi, or mycoplasma.). "In a recent preprint,PBX3 was found to be associated with pneumonia in almost 25,000 cases from UK Biobank and FinnGen48." (PMID 39220670, 2021).
tumor (56 papers, 2012 to 2026). "Concomitantly, PBX3 upregulation in clinical tumor patients is often associated with poor prognosis." (PMID 40508020, 2025). "Our results not only provide new insights regarding the regulation of tumor metabolic reprogramming but also a new perspective regarding the molecular mechanism underlying the oncogenic role of PBX3." (PMID 37781025, 2023). "In PaC cells, overexpression of Pbx3 is associated with tumor development and miR-129-5p prevents the proliferation and migration of cancer cells by targeting Pbx3." (PMID 33402862, 2020). "PBX3 has frequently been reported as having a role in the development and maintenance of a malignant phenotype, and high levels of PBX3 tumor expression have been linked to shorter overall survival in cancer." (PMID 32069812, 2020). "High PBX3 expression was significantly associated with tumor size, lymphatic metastasis, and TMN stage (all P < 0.05)." (PMID 32047817, 2020). "In other studies, ARNT2, CREB3L1, GLI3, and PBX3 have been associated with tumor progression." (PMID 33924679, 2021). "Notably, the upregulated PBX3 expression was associated with tumor size, lymphatic metastasis, and TMN stage (all P < 0.05) as well as overall survival time of PTC patients." (PMID 32047817, 2020). "PBX3 has been continuously reported to be associated with tumor growth and progression." (PMID 28934982, 2017). "PBX3 plays a pivotal role in tumor cell proliferation, apoptosis, and migration by regulating various cellular processes." (PMID 40508020, 2025). "Given the importance of lipid metabolism in highly proliferative tumor cells, we next assessed the possible involvement of PBX3 in tumor cell lipid metabolism." (PMID 40508020, 2025). "In this study, we revealed a novel function of PBX3 as a positive regulator of tumor cell cholesterol biosynthesis that promotes the transcriptional activity of HMGCR, and that PBX3/HMGCR-mediated cholesterol biosynthesis is crucial for its oncogenic activity." (PMID 40508020, 2025). "Herein, we found that PBX3 significantly promotes tumor growth by enhancing lipid accumulation in HCC cells." (PMID 40508020, 2025). "The knockdown of all transcription factors, except FoxJ3 and PBX3, attenuated the viability of tumor spheroids in response to cisplatin." (PMID 40860181, 2025). "In this study, to elucidate the role of PBX3 in regulating tumor cell lipid metabolic reprogramming, we investigated the effects of manipulating PBX3 expression on genes related with lipid metabolism and identified HMGCR as a novel target of PBX3." (PMID 40508020, 2025). "Among 12 tumors with known fusion partners, the fusions partner was CREB1 in 6 cases (50%), CREM in 4 tumors (33%), ATF1 in one tumor (8%) and PBX3 (8%) in another tumor." (PMID 40748380, 2025). "Furthermore, PBX3 could affect the expression of genes associated with cytoskeletal remodeling and extracellular matrix degradation, such as MMPs and vimentin, thereby promoting tumor cells’ metastatic potential." (PMID 40508020, 2025). "For example, high expression of PBX3 can promote tumor cell proliferation, invasion and migration, stem cell characteristics." (PMID 38324550, 2024). "Recent studies have shown that PBX3 is highly expressed in a variety of malignant tumors and is related to tumor cell proliferation, invasion, metastasis and resistance to radiotherapy and chemotherapy." (PMID 38324550, 2024). "We next examined the effect of knocking down PBX3 on tumor cell glucose consumption rate and lactate production levels." (PMID 37781025, 2023). "Our current findings show that PPP activation is crucial for PBX3-mediated tumorigenesis, linking PBX3 with tumor cell glucose metabolic reprogramming, thus further confirming its function as an oncogene." (PMID 37781025, 2023). "Together, these results suggested that PBX3 positively regulates PPP in tumor cells, thereby promoting their viability." (PMID 37781025, 2023).
tumor (continued). "Nevertheless, our current finding is the first that shows a crucial role of PBX3 in regulating tumor cell metabolic reprogramming through its regulation of G6PD." (PMID 37781025, 2023). "miR-320a enhances apoptosis and inhibits tumor growth by targeting pre-B-cell leukemia transcription factor 3 (PBX3)." (PMID 37829335, 2023). "Our present study reveals that PBX3 is essential for glucose metabolism in tumor cells, specifically, we identify PBX3 as a novel transcriptional regulator of G6PD that binds directly to the G6PD promoter and enhances its activity." (PMID 37781025, 2023). "PBX3 protein expression was significantly upregulated in HCC tumor tissues, and a high level of PBX3 expression in tumor tissues was also observed via IHC staining in the same microarrays containing 138 paired HCC specimens." (PMID 35509064, 2022). "In this study, we found that PBX3 expression was significantly upregulated in PTC tissues compared to adjacent normal tissues, and high levels of PBX3 were correlated with tumor size, lymphatic metastasis, TMN stage, and poor prognosis of PTC patients." (PMID 32047817, 2020). "In conclusion, our results demonstrated that PBX3 was upregulated in human PTC tissues and associated with tumor size, lymphatic metastasis, and TMN stage." (PMID 32047817, 2020). "Two miRs that target PBX3 at the post-transcriptional level both have tumor suppressor functions in AML." (PMID 32069812, 2020). "Consistently, knockdown of PBX3 by shRNA induced cell cycle arrest at G0/G1 phase, and inhibited angiogenesis and tumor growth in vitro and in vivo." (PMID 32047817, 2020). "The high expression levels of PBX3 and CACNA2D1 have been validated to be associated with tumor-initiating-cell (TIC) properties in the cell clone from the recurrent tumor." (PMID 32205176, 2019). "The miR-320a-PBX3 pathway inhibited tumor progression by suppressing the activation of the MAPK pathway in HCC." (PMID 29740327, 2018). "Downregulation of PBX3 consistently led to decreased tumor invasion compared with the control group." (PMID 30016974, 2018). "MiR-320a can be combined with the downstream target genes PBX3 as a tumor suppressor miRNA to inhibit the liver cancer cell proliferation, migration and metastasis." (PMID 29552328, 2018). "PBX3 (Pre-B cell leukemia homeobox 3), a putative target gene of miR-320, has been reported to be upregulated in various tumors and promote tumor cell growth through regulating MAKP/ERK pathway." (PMID 28934982, 2017). "In the literature, PBX3 is sufficient and necessary for the acquisition and maintenance of tumor-initiating cells (TIC) properties." (PMID 27285759, 2016). "Their group also demonstrated that PBX3 is targeted by multiple miRNAs and is essential for tumor-initiating liver cells." (PMID 27285759, 2016). "Furthermore, our findings demonstrate the potential of targeting PBX3 as an anti-tumor therapeutic strategy." (PMID 40508020, 2025). "The results showed a significant positive correlation between the expression of PBX3 with these genes, indicating that PBX3 might be correlated with tumor cell lipid metabolism." (PMID 40508020, 2025). "Furthermore, our findings also suggest the potential of targeting PBX3 for anti-tumor therapeutic strategy." (PMID 40508020, 2025). "Previous studies revealed that leukemia transcription factor 3 (PBX3) could promote tumor cell growth, survival, migration, and invasion potential." (PMID 40508020, 2025). "Despite its important roles as an oncogene, the role of PBX3 in regulating tumor cell lipid metabolic reprogramming remains unknown." (PMID 40508020, 2025). "In summary, we identified PBX3 as a novel regulator of tumor cell glucose metabolic reprogramming." (PMID 37781025, 2023).